VCAM1 (vascular cell adhesion molecule 1)
Diseases named in the same sentence as VCAM1 in open-access papers (continued):
Sharing a sentence is not in itself a finding about the gene and the disease.
infection (continued). "Our in vivo data demonstrating significant increase of ICAM-1, VCAM-1 and E-selectin in the brain at day 8 after infection correlates with the peak of inflammatory cytokines levels and suggest that this may be one of the downstream responses of virus-induced inflammation in the brain." (PMID 25036379, 2014). "Similarly, in the present study, we found a marked increase in ICAM-1 expression in the brain on day 6 of infection, VCAM-1 and P-selectin had more modest increases and E-selectin expression was not significantly different in uninfected and saline-treated mice." (PMID 21649904, 2011). "In contrast, untreated infection networks were dominated by inflammatory mediators (IL6, CXCL10, CCL2, VCAM1, SELE) and antiviral sensors (DDX58, OAS1, IFI44, IFI6), which reflect strong cytokine and interferon-driven immunity." (PMID 41480150, 2025). "In contrast, other molecules (VCAM-1, EPHB1, TMEM123, etc.)showed little inhibitory effect on infection within the density range we used." (PMID 41147561, 2025). "At three months post infection, hospitalized patients exhibited elevated levels of ICAM-1, VCAM-1, and IL-6, alongside a detectable immunoreactivity in SARS-CoV-2-specific T-cell response." (PMID 41226453, 2025). "Previous studies have demonstrated that TNF-α can stimulate endothelial cells to express adhesion molecules like VCAM-1 and ICAM-1 (Intercellular adhesion molecule-1), which are key to promoting inflammation during infection." (PMID 40431657, 2025). "We also evaluate the expression of VCAM1 and we observed that in HUVEC it increases, reaching a peak at hour 4 post-infection (7.5-fold comparing to uninfected cells) (p-value < 0.0001) and begins to reduce from hour 8 post-infection." (PMID 40141288, 2025). "Analysis of endothelial parameters revealed that Hispanic ethnicity was positively correlated with VCAM-1 and MPO which corresponds to elevated levels of these markers seen in severe infection." (PMID 37598150, 2023). "While CD28 Ab, VCAM-1 and MAdCAM-1 all promoted the formation of TRM-like cells, only MAdCAM-1 + RA costimulation consistently supported infection." (PMID 36897929, 2023). "Myoglobin (p = 0.02), VCAM1 (p < 0.0001), and myeloperoxidase (MPO) (p < 0.0001) were all significantly upregulated in the plasma of the severe infection group compared to healthy controls." (PMID 37598150, 2023). "Each validated index respectively combined with classical infection indexes of PCT and CRP, and only the combination of VCAM1 had AUC‐ROC of 0.745, which was better than that of VCAM1 (p = 0.018)." (PMID 34825737, 2022). "Multiple vascular adhesion proteins were induced rapidly during infection, such as CADM1, ICAM1, and VCAM1." (PMID 35913192, 2022). "Significantly increased expression of vascular cell adhesion molecule 1 (VCAM-1) and intercellular adhesion molecule 1 (ICAM-1) were found in the OB on day 6 of infection." (PMID 35510986, 2022). "Percentage of nucleated cells (leukocytes) found circulating in the brain vasculature at day 6 post-infection in mice treated with α−ICAM1, ICAM2, or VCAM1, relative to the isotype control (represented as 100%)." (PMID 35787830, 2022). "(A) Immunohistochemical (IHC) staining showed increased expression of endothelial VCAM-1 and ICAM-1 in the OB on day 6 of infection." (PMID 35510986, 2022). "Upon infection and activation, endothelial surface adhesion molecules E-selectin, intercellular cell adhesion molecule-1 (ICAM-1) and vascular cell adhesion molecule-1 (VCAM-1) are upregulated." (PMID 36203596, 2022). "In contrast, the infection of HAE drove a significant increase of the adhesion molecules E-selectin and VCAM-1 expression in ECs." (PMID 36139488, 2022). "Lastly, expression of VCAM-1, ligand for the integrin VLA-4, was significantly reduced in both WT and Tlr7−/y during the infection, but to a lesser extent in Tlr7−/y mice." (PMID 36278864, 2022).
infection (continued). "Our results showed that BAE cell infection by E. ruminantium resulted in the over-expression of several ECs surface proteins, such as ICAM1, VCAM1, CSF1, ESM1 and MCAM." (PMID 34073568, 2021). "Within 12 h of infection, we observed an almost complete shift of the CD31−CD45− FLS population towards ICAM-1+VCAM-1+ cells, indicating that more than 90% of all FLS expressed these adhesion molecules at a high level." (PMID 33117382, 2020). "The genes, Ccl2, Ccl20, Csf1, Cx3cl1, Cxcl1, Cxcl3, Il6, Birc3, Map3k8, Nos2, Nfkb2, Tnfrsf1b, and Vcam1, played core roles in a PPI network, and interacted closely with other ones in the infection." (PMID 33042984, 2020). "Infection of C57BL/6 mice with WNV NY strain also resulted in increased expression of ICAM-1, VCAM-1, and E-selectin in the brain." (PMID 30984122, 2019). "The present study showed that the infection with PbA increased ICAM-1 and VCAM-1 mRNA expression in the brain of infected mice." (PMID 29367729, 2018). "These factors include OSM, IL-4 (gene up-regulated on day 1 post infection) and MIF (macrophage migration inhibitory factor) that induces P- and E-selectin and vascular cell adhesion molecule 1 (VCAM-1)." (PMID 25719526, 2015). "Analysis of CAMs response to Eg101 demonstrated that mRNA of all three CAMs, ICAM-1, VCAM-1 and E-selectin were induced in infected HBMVE cells at 48 hrs time point, which further increased at 72 hrs after infection." (PMID 25036379, 2014). "Infection with WNV (NY99 strain) significantly induced ICAM-1, VCAM-1, and E-selectin in human endothelial cells and infected mice brain, although the levels of their ligands on leukocytes (VLA-4, LFA-1and MAC-1) did not alter." (PMID 25036379, 2014). "IFN- γ also induces the expression of vascular cell adhesion molecule-1 (VCAM-1), which enhances the recruitment of CD4+ T cells and CD8+ T cells to the site of infection." (PMID 25404878, 2014). "Increase in the mRNA levels of ICAM-1, VCAM-1 and MCP-1 was observed on addition of CRP or high glucose and infection with IGFBP-3 significantly decreased these levels." (PMID 23383064, 2013). "Circulating concentrations of lymphotactin, MIP-1γ, MPO, MMP9, as well as VCAM-1, CRP, SAP, and haptoglobin were altered with Hb-infection and reduced in Hb-infected mice treated with anti-IL-7Rα M595." (PMID 23057802, 2012). "Increased expression of VCAM-1 and ICAM-1 was observed from 24 h post-infection, but the most prominent changes were observed at day 7 after infection." (PMID 22738332, 2012). "Since contrary data exist about the role of ICAM-1 and VCAM-1 in PMN adhesion and transmigration we were interested in their role on PCPECs after infection with S. suis." (PMID 21592385, 2011). "Furthermore, IL-1β enhances the expression of adhesion molecules, including intercellular adhesion molecule-1 (ICAM-1) and vascular cell adhesion molecule-1 (VCAM-1), which facilitate immune cell recruitment to the site of infection or injury." (PMID 40155968, 2025). "Furthermore, the expression of vascular cell adhesion molecule-1 (Vcam1) mRNA, an endothelial activation marker, was significantly elevated in WT (p < 0.05) and eNOS+/− mice following MA10 infection." (PMID 40573374, 2025). "Also, infection of the THP-1 monocytes upregulates integrin LFA-1 and MAC-1, the ligand of ICAM-1, and VLA-4, the ligand of VCAM-1, which promotes the transmigration of monocytes across the BBB." (PMID 39840010, 2024). "No alterations were observed on VCAM-1 and MCP-1 expressions, neither caused by infection nor LOV treatment." (PMID 38785783, 2024). "In this case, A. lancea and Prabchopoothaweep remedy alone downregulated the production of ICAM-1, VCAM-1, and CD36 on day 13 post-infection, while the expression of ICAM-1, VCAM-1, and CD36 was significantly lower than that in the Art-AL and Art-PT combination treatment groups." (PMID 37730604, 2023).
infection (continued). "Notably, our results showed an upregulated transcriptional expression of cytokines (IL-1β, IL-6 and TNF-α), adhesion molecules (VCAM-1, ICAM-1) and chemokines (CXCL1 and CXCL2) after infection in both brain cortex and hippocampus." (PMID 36778380, 2023). "The significant positive correlation between HCV-infection and VCAM-1 and negative correlation between cART use and VCAM-1 was confirmed in multivariate analyses." (PMID 35159966, 2022). "In addition, we show that within the peritoneal membrane lined by peritoneal mesothelial cells (PeM), the gene expression levels of cell adhesion markers VCAM-1 and ICAM-1 decrease significantly in response to a secondary infection." (PMID 35418979, 2022). "In addition, at day 3 after the last infection, immunolocalization assay showed that anti-CD90.2 antibody-treated mice displayed a reduced expression of VCAM-1 in vessels of the vaccination region compared to that of the isotype-treated mice." (PMID 32411786, 2020). "Increased expression of the adhesion molecules VCAM-1 and E-selectin was observed at the peak of WNV replication, suggesting that the infection of endothelial cells might facilitate the migration of leukocytes." (PMID 30984122, 2019). "Likewise, host immune-related genes, such as VCAM1, NFKB1 and TLR2/3, were also elevated at the early stage in the infection group, which were consistent with many previous reports." (PMID 28486945, 2017). "Infection with live, wild‐type (WT) N. meningitidis leads to a marked increase in E‐selectin, Intracellular Adhesion Molecule‐1 (ICAM‐1) and Vascular Adhesion Molecule‐1 (VCAM‐1) endothelial expressions." (PMID 26153406, 2016). "After infection of HCAEC with T. cruzi, we observed increased cell surface expression of intercellular adhesion molecule‐1 (ICAM‐1), vascular cell adhesion molecule‐1 (VCAM‐1), and E‐selectin prior to the observed increase in PAF production." (PMID 24744875, 2014). "Therefore, cell culture supernatants collected at 24 h post infection were analyzed for the presence of MCP-1, IL-8, IL-6, GM-CSF, and soluble cell adhesion molecules (ICAM-1, VCAM-1, and E-selectin)." (PMID 24069284, 2013). "We also show that ~95% depletion of c-KIT transcript levels by siRNA treatment rescued EGR1, VCAM1, CCL20, and IL-8 gene expression in response to Y. enterocolitica WA infection in THP-1 cells, compared to infected control cells treated with non-targeting siRNA (si-CTL)." (PMID 24206648, 2013). "Whatever the reasons, a consequence is that mechanisms for promoting entry of systemic antigen-specific cells, such as up-regulation of VCAM-1, are not activated until two weeks post-infection." (PMID 20011050, 2009). "To test whether VCAM-1/VLA-4 interactions play a direct role in DC IL-12p40 production, we blocked these molecules 12 hours prior to infection and measured IL-12p40 mRNA levels in DC isolated from the spleen at 5 hours p.i.." (PMID 18802456, 2008). "TNF may then activate endothelial cells by promoting the expression of adhesion molecules like intercellular adhesion molecule 1 (ICAM-1), vascular cell adhesion molecule 1 (VCAM-1), and the secretion of chemokines that attract immune cells to the site of infection." (PMID 40283058, 2025). "The infection of the HBMECs induces overexpression of surface adhesion molecules, intracellular adhesion molecule-1 (ICAM-1), vascular cellular adhesion molecule-1 (VCAM-1), VE-cadherin, N-cadherin, and β-catenin, and downregulates Occludin which is a tight junction membrane protein." (PMID 39840010, 2024). "While alternative HAdV receptors VCAM-1 and SR-A are constitutively expressed by bone marrow-derived cells, MHC class molecules are upregulated upon maturation of BMDCs, which might contribute to the higher infection rate." (PMID 35062296, 2022). "Furthermore, we observed that leukocytes also expressed increased ICAM1 (fivefold) and ICAM2 (twofold), but not VCAM1, upon infection with either strain." (PMID 35787830, 2022).
infection (continued). "For one, the infection of aortic lesions with P. gingivalis activates adhesion molecules such as intercellular adhesion molecule 1 (ICAM-1) and vascular cell adhesion molecule 1 (VCAM-1), leading to chronic inflammation via migration of more immune cells to the lesion sites." (PMID 35406643, 2022). "Some of these genes belong to the NF-kappa B (NF-κB) (PLAU, VCAM1, TNFRSF1A) and/or mitogen-activated protein kinase (MAPK) (TNFRSF1A and PGF) signaling pathways, indicating a differential regulation of the inflammatory response in lungs for both infection outcomes." (PMID 35003125, 2021). "As compared to the mock-infected controls, the mRNA transcripts of ICAM-1, VCAM-1 and E-selectin in the brain did not change at day 4 after infection (data not shown), however a 2- to 9-fold increase was observed at day 6, which further increased at day 8 after infection." (PMID 25036379, 2014). "However, there was no significant increase in the expression of VCAM-1 in both WT and db/db mice after infection." (PMID 24750819, 2014). "Interestingly, Cnr1-/- mice showed enhanced microglial reactivity and VCAM-1 expression following TMEV infection, indicating that the lack of CB1 receptor exacerbated neuroinflammation." (PMID 21851608, 2011). "In addition, the CD8+ DC are capable of acquiring L. donovani amastigotes independent of VCAM-1 early after infection, and these infected cells are able to produce IL-12p40 (Maroof, unpublished)." (PMID 18802456, 2008). "We also observed that a small proportion of CD8+ DC were infected with L. donovani amastigotes at 5 hours p.i., and that infection of these cells was not reduced by anti-VCAM-1 mAb (0.50±0.10% versus 0.37±0.11% for mice receiving rat IgG or anti-VCAM-1 mAb, respectively, determined from cytospins)." (PMID 18802456, 2008). "To determine whether VCAM-1/VLA-4 interactions play a direct role in cellular recruitment to the liver following L. donovani infection, we delayed VCAM-1 or VLA-4 blockade until 3 days after infection." (PMID 18802456, 2008). "Up-regulation of adhesion molecules like intercellular adhesion molecule 1 (ICAM-1) or vascular cell adhesion molecule-1 (VCAM-1) in pulmonary epithelium was observed after exposure to diverse stimuli such as LPS, outer membrane protein A from K. pneumoniae or infection with P. carinii." (PMID 16827942, 2006). "Notably, ICAM-1 and VCAM-1 signal were detected in infected mice in regions both with and without T. gondii parasites, indicating a global effect of infection on endothelial cell activation, likely due to systemic inflammation-induced upregulation of these adhesion molecules." (PMID 39780244, 2025). "Here, we verified the effect of LOV on these mediators and observed that treatment prevented the increase in ICAM-1 levels, but VCAM-1 and MCP-1 levels were not affected by either infection or treatment." (PMID 38785783, 2024). "Similar, also mice with T. cruzi infection express significantly more VCAM-1 and ICAM-1 on their cardiac endothelium compared to mice without infection." (PMID 29536322, 2018). "After KFDV infection of the cells (MOI 10), ICAM1 was most noticeably expressed (with 20.0% ICAM1–positive cells), whereas E-selectin and VCAM1 production were not so prominent (10.7 and 9.8% positive cells, respectively)." (PMID 30401896, 2018). "Fibronectin and vitronectin reproducibly inhibited infection in these experiments by up to 40%, whilst LAMB1, ICAM-1, VCAM-1 or heparan sulphate did not affect the efficiency of infection." (PMID 21573183, 2011). "Because the cells harvested at six days post-infection persisted in culture as non-adherent cells, we chose to investigate surface expression of the adhesion markers intercellular adhesion molecule-1 (ICAM-1, CD54) and vascular cell adhesion molecule-1 (VCAM-1, CD106)." (PMID 18787698, 2008).
cardiovascular disease (96 papers, 2009 to 2026). "Due to these properties, VCAM-1 is a diagnostic biomarker used in many clinical studies to estimate endothelial dysfunction, which is a risk factor for cardiovascular diseases." (PMID 35336985, 2022). "The research concluded that a diet rich in ALA plays a role in reducing multiple cardiovascular disease risk factors such as decreasing pro inflammatory cytokines, changes in VCAM-1, lowering cholesterol levels or increasing EPA levels in serum." (PMID 31228942, 2019). "Some studies suggest that increased levels of VCAM1 may have a protective effect on cardiovascular disease risk." (PMID 38338971, 2024). "The results presented here indicate the necessity for extending conventional guideline-based risk stratification scores by adding novel biomarkers, such as VCAM-1, to further improve the risk stratification and guide treatment eligibility for cardiovascular disease prevention in the OSA population." (PMID 38255155, 2023). "In cardiovascular disease, lipid deposition and associated endothelial cell damages such as increased Vascular Cell Adhesion Molecule-1 (VCAM-1) and Monocyte Chemoattractant Protein-1 (MCP-1) expression are significant contributors that set the stage for further aggravation." (PMID 37242746, 2023). "Interestingly, increased levels of endothelial activation markers ICAM-1 and VCAM-1 have been associated with cardiovascular disease in both the uninfected and in the HIV-infected population." (PMID 32575428, 2020). "Air pollution was linked to changes in markers of coagulation (fibrinogen), inflammation (C-reactive protein), and endothelial function (ICAM-1 and VCAM-1), that may influence risk of cardiovascular disease." (PMID 31703266, 2019). "VCAM-1 have been used for risk assessment for future cardiovascular disease." (PMID 29641752, 2018). "This is also true for the perioperative setting, where an association of high preoperative VCAM1 levels with long-term (median follow-up of 6.7 years) all-cause mortality could be found in patients suffering from cardiovascular disease undergoing on-pump cardiac surgery." (PMID 38379859, 2023). "VCAM1 (Vascular Cell Adhesion Molecule 1) mainly encodes a cell surface sialoglycoprotein expressed by cytokine-activated endothelium and mediates leukocyte-endothelial cell adhesion and signal transduction that has been extensive-studied in cardiovascular diseases." (PMID 35966076, 2022). "The recruitment of immune cells to the endothelium is a pivotal event in the progression of cardiovascular disorders, involving various adhesion molecules, with VCAM-1 serving as a key mediator of this process." (PMID 40943070, 2025). "ALA reduces the risk of cardiovascular disease risk, possibly by favorably modifying vascular inflammation, with reduced levels of CRP, vascular cell adhesion molecule-1 (VCAM-1), E-selectin, serum total cholesterol, LDL and triglyceride levels." (PMID 38605945, 2024). "PCA sulfate lower the production of interleukin-6 (IL-6) and vascular cell adhesion molecule-1 (VCAM-1), pro-inflammatory cytokine genes that are linked to cardiovascular diseases." (PMID 38958528, 2024). "ICAM-1 and VCAM-1’s interaction with NF-kB activation assumes crucial significance in this context, particularly in cardiovascular diseases, where heightened levels of these adhesion molecules exacerbate vascular inflammation and dysfunction." (PMID 39513877, 2024). "Our results contribute to emerging evidence from a small number of studies linking PGF, TNC and VCAM1 with cardiovascular disease in people with CKD." (PMID 38162538, 2024). "Elevated sVCAM1 levels have been found to be associated with poor cardiovascular disease (CVD) outcomes, supporting VCAM1’s role as a potential diagnostic marker and therapeutic target." (PMID 37762417, 2023). "As a therapeutic delivery method for VCAM-1, high expression in cardiovascular disease shows considerable promise for application." (PMID 37242620, 2023).